CP (ceruloplasmin)
Diseases named in the same sentence as CP in open-access papers (continued):
Sharing a sentence is not in itself a finding about the gene and the disease.
retinal degeneration (8 papers, 2012 to 2025). Degeneration of the retina. "Aceruloplasminaemia is a very rare autosomal recessive disorder caused by a mutation in the ceruloplasmin gene, which is clinically manifested by damage to the nervous system and retinal degeneration." (PMID 32264837, 2020). "Ceruloplasmin-deficient mice have hereditary iron overload and also show features of retinal degeneration." (PMID 23825457, 2013). "In a previous study, it was theorized that the low serum levels of CP coupled with high iron levels led to retinal degeneration, as CP might help to prevent the oxidative damage caused by ferrous iron by oxidizing iron from its ferrous to ferric form." (PMID 40650085, 2025). "Furthermore, administration of anti-FD antibody into C4-deficient mice protected against NaIO3-induced retinal degeneration, suggesting that combined blockade of the CP/LP and AP is required to optimally prevent dry AMD-like disease in mice." (PMID 40226626, 2025). "Similarly, mice with targeted mutation of the iron exporter ceruloplasmin and its homolog hephaestin showed age-related retinal iron accumulation and retinal degeneration with features resembling human age-related macular degeneration (AMD)." (PMID 23825457, 2013). "This is atypical for patients with HH, so it was theorized that the low serum levels of ferroxidase ceruloplasmin (CP) of this patient coupled with the high iron levels led to the retinal degeneration." (PMID 37439255, 2023). "If so, this would suggest that CP levels play an important role in influencing retinal degeneration." (PMID 37439255, 2023). "Indeed, it has been reported that the CP is involved in the development of NaIO3-induced retinal degeneration." (PMID 40226626, 2025). "These protective findings suggest that CP levels might influence the severity of retinal degeneration, especially at the initial stages of ERM." (PMID 40650085, 2025). "The findings suggest that CP levels may influence the severity of retinal degeneration, especially in individuals with high serum iron." (PMID 37439255, 2023). "Several studies have shown the neuroprotective effects of DFP on different retinal degeneration models induced by sodium iodate, tunicamycin and light as well as Ceruloplasmin/Hephaestin double-knockout mice and hereditary retinal degeneration caused by the rd6 mutation." (PMID 36385152, 2022). "In retinal degeneration induced by sodium iodate (NaIO3), a murine model of dry AMD (also called atrophic AMD), it has been suggested that the AP and CP are involved in the disease development." (PMID 40226626, 2025). "Mice lacking key genes of iron homeostasis – ceruloplasmin, hephaestin and hepcidin — developed retinal degeneration with features of AMD." (PMID 22371024, 2012).
steatosis (8 papers, 2021 to 2025). Increased lipid within the cytoplasm of cells. "Despite the important diagnostic value in Wilson's disease, some studies suggested serum CP was inversely correlated to fibrosis or positively associated with steatosis in hepatitis B patients." (PMID 35795637, 2022). "Proteins such as orosomucoid-1 (ORM1) and ceruloplasmin have been identified as potential biomarkers capable of distinguishing mild steatosis from healthy individuals and differentiating severe steatosis from mild cases in MASLD patients." (PMID 40427524, 2025). "Patients with steatosis: low ceruloplasmin (<14 mg/dL); increased 24-h urinary copper excretion (>100 μg/24 h); increased non-ceruloplasmin-bound copper; and increased hepatic copper levels (>250 μg/g)." (PMID 40197188, 2025). "Ceruloplasmin (ROC 0.79, p = 0.028) and ORM1 (ROC 0.81, p = 0.019) also showed moderate diagnostic accuracy in distinguishing severe steatosis from mild steatosis." (PMID 35741222, 2022). "On the contrary, some researchers found that Cu is elevated in visceral adipose tissue and liver, with little steatosis in obese patients, likely due to the concurrent increase in ceruloplasmin." (PMID 35741222, 2022). "ORM1 and ceruloplasmin are potential biomarkers to distinguish mild steatosis from healthy controls, and severe steatosis from mild steatosis, in patients with MAFLD." (PMID 35741222, 2022). "A comparison of the two groups showed that the severity of steatosis, hepatocellular ballooning, inflammation activity, fibrosis, and liver iron deposition decreased along with the CP ratio (p < 0.05)." (PMID 35795637, 2022). "The proportion of steatosis >66% in the low CP ratio group was significantly greater than that in the high CP ratio group (30.4% vs. 15.9%, p = 0.044)." (PMID 35795637, 2022). "Ceruloplasmin from cluster three (up-regulated panel) was 3.1-fold higher in mild steatosis and 4.8-fold higher in severe steatosis." (PMID 35741222, 2022). "According to ELISA and western blot (30 urine samples, normalized to urine creatinine), ceruloplasmin (ROC 0.78, p = 0.034) and ORM1 (ROC 0.87, p = 0.005) showed moderate diagnostic accuracy in distinguishing mild steatosis from healthy controls." (PMID 35741222, 2022). "Similarly, SLC40A1, the gene encoding the iron exporter ferroportin, was lower in steatosis and NASH than in HOC, and caeruloplasmin (CP) was decreased in NASH compared to both control groups." (PMID 34869521, 2021). "The treatment of CpKO mice with ceruloplasmin limited liver iron accumulation and steatosis without normalizing the expression of iron homeostasis-related proteins." (PMID 36674661, 2023).
dyslipidemia (7 papers, 2016 to 2025). "High ceruloplasmin levels are associated with type I/II diabetes, metabolic syndrome and other recognized risk factors for cardiovascular disease." (PMID 37301835, 2023). "High ceruloplasmin levels have been associated with type I and type II diabetes, metabolic syndrome, and other well-established CVD risk factors, suggesting that it has a more predominant role in signaling pathways than in exerting antioxidant properties." (PMID 30147446, 2018). "Due to dyslipidemia also being considered a risk factor for cardiovascular diseases, we expected to find increased ceruloplasmin activity associated with dyslipidemia." (PMID 30487467, 2018). "The mechanisms linking copper deficiency to dyslipidemia remain unclear, but proposed pathways involve its role as a cofactor for enzymes like superoxide dismutase and ceruloplasmin, which regulate oxidative stress and cholesterol transport." (PMID 40172775, 2025).
glioblastoma (7 papers, 2014 to 2024). The most malignant astrocytic tumor (WHO grade IV). "Our CP-model indicated an inextricable link between copper-dependent cell death and tumor immune responses in glioblastoma when seen as a whole." (PMID 38606090, 2024). "This study developed a prognostic signature using hypoxia-related differentially expressed genes (DEGs) in Glioblastoma Multiforme (GBM) and identified three optimal gene signatures (CP, IGFBP2, and LOX) using multi-omics analysis." (PMID 38339384, 2024). "Vice versa, transfection of the human glioblastoma cell line U-373 MG with a C/EBPD expression vector led to a significant upregulation of C3, CXCL9, CP, CCL3, TNFAIP6, and IL-6 mRNA levels." (PMID 26230261, 2015).
Hypertension (7 papers, 2013 to 2025). The presence of chronic increased pressure in the systemic arterial system. "In multivariate analysis, only age (OR 1.04; 95% CI, 1.02–1.06; P < 0.01) was significantly associated with the number of CP + sites, with a trend towards significance for hypertension (OR 1.40; 95% CI, 0.99–1.98; P = 0.06)." (PMID 37147478, 2023). "In univariate regression analysis, arterial hypertension (OR 1.63; 95% CI, 1.09–2.32; P = 0.02) and age (OR 1.04; 95% CI, 1.03–1.06; P < 0.01) showed significant associations with the number of CP + sites." (PMID 37147478, 2023). "Despite those associations between morphology-based alterations and functional imaging, only the number of CP + sites was associated with CVRFs (including age and arterial hypertension), but not the FAPI PET signal." (PMID 37147478, 2023). "Ceruloplasmin (CP) levels were also found increased in patients with hypertension and albuminuria." (PMID 28562335, 2017).
liver cirrhosis (7 papers, 2013 to 2025). "In 17 patients with liver cirrhosis, the OS at 6, 12, 18, and 24 months for CP class A was 100%, 87.5%, 87.5%, and 87.5%, respectively, while that for CP class B was 100%, 66.7%, 66.7%, and 33.3%, respectively." (PMID 39873460, 2025). "Our model uses routinely assessed markers in combination with CP levels to reliably predict the probability of liver cirrhosis." (PMID 24282481, 2013). "Based on the indirect association between the levels of CP and the stage of fibrosis in CHB patients, we used a combination of biochemical markers and serum CP levels to construct a model and a scoring system to distinguish patients with and without liver cirrhosis." (PMID 24282481, 2013).
liver dysfunction (7 papers, 2017 to 2023). "Aceruloplasminemia, caused by pathogenic variants in the ceruloplasmin gene compromising its ferroxidase activity and preventing cellular Fe efflux, is characterized by adult-onset diabetes, retinopathy, hepatopathy, and neuropsychiatric symptoms." (PMID 35625641, 2022). "In our report, we describe the case of a patient with aceruloplasminaemia detected in an early stage (without clinical symptoms of damage to the nervous system) during the search for the cause of hepatopathy with very low values of serum ceruloplasmin." (PMID 32264837, 2020). "Although this allowed a uniformized CP scoring, it might have biased clinical CP class assignments as our measure of liver dysfunction." (PMID 37003973, 2023). "Of the 1,118 patients with liver dysfunction, 27.10% had ceruloplasmin levels <0.20 g/L." (PMID 36570465, 2022). "These include hepatopathy with low serum ceruloplasmin and low serum copper." (PMID 29321044, 2018).
mild cognitive impairment (7 papers, 2013 to 2025). "Collectively, these results demonstrate that PE ameliorates scopolamine (1 mg/kg)-induced cognitive impairment by enhancing synaptic plasticity, likely through modulation of mAChR, CP-AMPAR, and NMDA receptor signaling." (PMID 41155218, 2025). "A good example of this is that despite there being limited presence of the soluble form of CP in the interstitial fluid, non-neuronal CP depletion causes age-dependent neuronal iron accumulation and cognitive impairment." (PMID 24795635, 2014). "Notably, a lower level of ceruloplasmin ferroxidase activity in the blood of subjects with mild cognitive impairment, compared to controls, has been observed, while copper transport into the brain has been found to be aggravated by increased concentrations of circulating non-ceruloplasmin copper." (PMID 37176104, 2023). "However, Rembach (2013) has suggested the possibility of decreased non-CP copper levels-copper that is not bound to ceruloplasmin in mild cognitive impairment (MCI) and AD, which leads to a decline of copper-dependent biochemical activities in AD, such as reducing SOD1 activity of erythrocytes." (PMID 33081348, 2020).
nosocomial infection (7 papers, 2019 to 2024). An infection acquired in a hospital or other healthcare setting. "This study highlights the genetic versatility of CP-Eco and its potential to disseminate ARGs and cause community and nosocomial infections." (PMID 38817448, 2024). "Carbapenemase-producing Klebsiella pneumoniae (CP-Kpn) are a major concern for nosocomial infections." (PMID 35546482, 2022). "The presence of carbapenem-producing Klebsiella pneumoniae (CP-Kp) is a serious threat to the control of nosocomial infections." (PMID 31440476, 2019). "Serratia marcescens, Citrobacter freundii, Providencia spp., and Morganella morganii (CP-ESCPM) are increasingly identified as causative agents of nosocomial infections but are still not under systematic genomic surveillance." (PMID 38786183, 2024). "Carbapenemase-producing carbapenem-resistant Pseudomonas aeruginosa (CP-CRPA) was detected only in this fifth serial sputum specimen, suggesting hospital-acquired infection." (PMID 37535466, 2023). "Since patients carrying non-CP CRE isolates are not cohorted in Israeli hospitals as CPE carriers, such misidentifications increase the potential for hospital cross-infection and outbreaks." (PMID 33126924, 2020).
pneumonia (7 papers, 2016 to 2024). An acute, acute and chronic, or chronic inflammation focally or diffusely affecting the lung parenchyma, caused by an infection in one or both of the lungs (by bacteria, viruses, fungi, or mycoplasma.). "Lastly, to evaluate the risk factors of severe AdV-infected pneumonia, multivariate logistic regression analysis was carried out by using AdV infection as an independent variable, and patient's age, sex, bacteria, MP, CP, and fungi as covariates." (PMID 38357505, 2024). "The most frequently associated infection with CP-Kp/iuc strains was pneumonia (n = 7), followed by osteomyelitis (n = 4)." (PMID 39365038, 2024). "Meanwhile, the risk factors for MP-induced severe pneumonia included sex, age, and coinfection with bacteria, CP or AdV." (PMID 38357505, 2024). "In bloodstream infections, colistin-based regimens showed a significant advantage while in pneumonia caused by CP-CRE, regimens containing tigecycline showed some advantages." (PMID 35884196, 2022). "In this study, we observed that RNA levels of genes encoding for the expression of ferritin, ceruloplasmin, lactoferrin and haptoglobin are increased 4 to 20 fold during P. aeruginosa acute pneumonia." (PMID 27982111, 2016). "High levels of Cu could increase the risk of infections such as pneumonia via increased inflammation, given its close relationship with ceruloplasmin, which is elevated during an acute phase response, in addition to the ability of Cu to serve as a nutrient for infectious microbes." (PMID 35781862, 2022). "Among those infected with CP-CRE, when comparing the risk of mortality in the different sites of infection, the highest risk was found in pneumonia, followed by bloodstream infection, with a p-value < 0.001." (PMID 35884196, 2022). "We speculate, that it is most likely caused by additional complications in the ICU patients, such as renal failure, severe pneumonia, or embolism, as well as an exhausted immune response with complement consumption (declining C3, C4, AP and CP activity, as also shown in our previous publication." (PMID 37051252, 2023). "Infection with CP-CRE presented a higher mortality compared to that with CSE, especially in terms of bloodstream infections and pneumonia." (PMID 35884196, 2022). "Colistin-based regimens showed a significant advantage (p = 0.03) in bloodstream infections caused by CP-CRE, whereas regimens containing tigecycline showed some advantage in pneumonia caused by CP-CRE, although this was not statistically significant (p = 0.28)." (PMID 35884196, 2022).
renal cell carcinoma (7 papers, 2012 to 2024). "Moreover, high expression levels of CP are correlated with malignant potential in esophageal cancer, bile duct cancer, renal cell carcinoma, and adrenocortical carcinoma." (PMID 38339384, 2024). "Additionally, ceruloplasmin is a predictive biomarker of PAX8 activity, and renal cell carcinoma (RCC) patients with high ceruloplasmin expression have a poor survival rate independent of genetic aberrations." (PMID 34413268, 2021). "However, in kidney (renal cell) cancer, a negative correlation was observed for both IP and CP expression with the CD45 expression, which could be due to the lack of cytotoxic or interferon signalling in the TME." (PMID 37097039, 2023).
Thrombocytopenia (7 papers, 2009 to 2026). A reduction in the number of circulating thrombocytes. "Laboratory studies revealed thrombocytopenia, mild aminotransferase elevation, profoundly reduced ceruloplasmin, and low serum copper." (PMID 41727798, 2026). "However, other mechanisms could also contribute to the thrombocytopenia, since some patients have antibodies that cross-react with platelets and endothelial cells and therefore augment the cytotoxicity mediated by the CP." (PMID 19707565, 2009).
bacteremia (6 papers, 2015 to 2025). "We found that non-CP-CRE isolates caused the vast majority of our CRE bacteremia cases and harbored MGEs with complex arrangements primarily of ESBLs, such as blaCTX-M variants, mediated by either IS26 or ISEcp1 elements." (PMID 36036505, 2022). "The high percentage of non-CP-CRE in our cohort was particularly interesting given that we only examined bacteremia isolates which are sufficiently fit to cause a serious infection inasmuch as non-CP-CRE isolates are often considered to have a fitness defect relative to CPE strains (44, –, 46)." (PMID 36036505, 2022). "In an observational study, patients with CPE bacteremia demonstrated a more than four times 14-day mortality rate when compared with non-CP-CRE bacteremic patients (aOR 4.92; 95% CI 1.01–24.81)." (PMID 34690758, 2021). "A previous study showed that CP-CRE caused higher mortality than non-CP-CRE in patients with bacteremia; however, CP-CRE had higher resistance rates against antibiotics other than carbapenems and higher MIC for carbapenems than non-CP-CRE in that study." (PMID 39881424, 2025). "While many studies have documented how an increase in AMR gene copy number corresponds to an increased AMR phenotype (13, –, 17, 33), to our knowledge, our study is the first to systematically demonstrate an ESBL gene copy number increase in a large cohort of non-CP-CRE bacteremia isolates." (PMID 36036505, 2022). "Non-CP-CRE strains were the most common cause of CRE bacteremia with carbapenem nonsusceptibility driven by concurrent porin loss and MGE-mediated amplification of blaCTX-M genes." (PMID 36036505, 2022). "The reasons underlying the high prevalence of non-CP isolates in our bacteremia cohort are not currently known but may include relatively stringent infection control practices among our highly immunocompromised patients." (PMID 36036505, 2022). "Our findings suggest that at the low inoculum present in bacteremia, PD-CRE exhibit higher carbapenem MICs than CP-CRE, yet clinical outcomes are similar or worse for CP-CRE bacteremia." (PMID 41036946, 2025). "There were 28 unique carbapenem-nonsusceptible K. pneumoniae (CNSKp) bacteremia isolates with eight CPKp (29%), 18 non-CP-CRKp (64%), and two CIKp (7%)." (PMID 36036505, 2022). "There were 37 unique carbapenem-nonsusceptible E. coli (CNSEc) bacteremia isolates with 6 CPEc (16%), 19 non-CP-CREc (51%), and 12 CIEc (32%)." (PMID 36036505, 2022).
clear cell renal cell carcinoma (6 papers, 2020 to 2024). "Additionally, the expression of ceruloplasmin (CP) was significantly linked to high-grade and a worse prognosis in clear cell renal cell carcinoma 46, which is similar to other EC study 19 and our results." (PMID 38385087, 2024). "The expression of plasma ceruloplasmin was also significantly upregulated in high-grade clear cell renal cell carcinoma samples." (PMID 36147484, 2022). "In hypoxic conditions, Ceruloplasmin (CP) induces generates oxygen radicals, while inducing activation of HIF-1α, Overexpression of CP in clear cell renal carcinoma is linked to oncogenic pathways and worse survival rates." (PMID 35924146, 2022). "Ceruloplasmin expression is also reported to be increased more than 10-fold in high-grade clear cell renal cell carcinoma samples." (PMID 34413268, 2021). "To further verify the reliability of the results, we experimentally demonstrated that the mRNA and protein levels of CP in clear renal cell carcinoma were significantly higher than those of CP in normal renal tissue, and cellular experiments showed similar results." (PMID 34449964, 2021).